SP1 (Sp1 transcription factor)
Diseases named in the same sentence as SP1 in open-access papers (continued):
Sharing a sentence is not in itself a finding about the gene and the disease.
Hypertension (8 papers, 2016 to 2025). The presence of chronic increased pressure in the systemic arterial system. "Tamoxifen-induced deletion of endothelial Sp1 and Sp3 in male mice decreases the serum nitrite/nitrate level, impairs endothelium-dependent vasodilation, and causes hypertension and cardiac remodeling." (PMID 37735515, 2023). "Additionally, studies in an Italian European cohort have suggested that a single C>G mutation in the GNAI2 promoter region reduces the binding of the specificity protein 1 (Sp1) transcription factor and is associated with hypertension." (PMID 35837296, 2022). "Given the detrimental effects of the TGF-β1/Smad/Sp1 axis on synaptic function and cognition in AngII-related hypertension, targeting this pathway may offer a promising strategy for treating AngII-related hypertension associated cognitive dysfunction." (PMID 40425782, 2025). "Here, we show that targeted deletion of endothelial Sp1 and Sp3 in male mice leads to a reduction in serum nitrite/nitrate levels, a disruption in endothelium-dependent vasodilation, and the onset of hypertension and cardiac remodeling." (PMID 37735515, 2023). "In the endothelium of mesenteric arteries from patients with hypertension, Sp1 and Sp3 were notably downregulated when compared to those from healthy individuals." (PMID 37735515, 2023). "This study demonstrated that Sp1/Sp3 protect against endothelial dysfunction and hypertension, enhancing our understanding of the functions of Sp1 and Sp3." (PMID 37735515, 2023). "Here, the authors show deletion of endothelial Sp1 and Sp3 leads to a disruption in endothelium-dependent vasodilation and the onset of hypertension, which abolishes the beneficial actions of captopril." (PMID 37735515, 2023). "In this study, we demonstrated that endothelial-specific Sp1/Sp3 deletion resulted in endothelial dysfunction and hypertension, and that captopril, an ACE inhibitor and traditional antihypertensive drug, exerted part of its pharmacological effect by modulating Sp1/Sp3 levels in endothelial cells." (PMID 37735515, 2023). "Given the critical roles of Ang II, endothelin-1 (ET-1), and H2O2 in hypertension and vascular diseases, we aimed to explore whether they regulate the expression of Sp1 and Sp3 in endothelial cells." (PMID 37735515, 2023). "Ang II, ET-1, or H2O2-mediated Sp1/Sp3 downregulation in endothelial cells may be a common mechanism in the early development of hypertension." (PMID 37735515, 2023). "To determine whether Sp1 and Sp3 are involved in the pathogenesis of endothelial dysfunction and hypertension, we detected their expression in the endothelium of mesenteric arteries from hypertensive patients and hypertensive mouse arteries." (PMID 37735515, 2023). "Indeed, endothelial Sp1 and Sp3 were responsible for the anti-hypertension and anti-endothelial dysfunction effects of captopril, which is the major finding of this study." (PMID 37735515, 2023). "Given that silencing or suppression of the Sp1 gene can result in significant endothelial dysfunction and hypertension, it is posited that endothelial aging and apoptosis may be mitigated by augmenting Sp1 expression through USP7-mediated deubiquitination and HDAC1-mediated deacetylation." (PMID 39252788, 2024). "Therefore, the reduction of Sp1 and Sp3 expression may crucially contribute to endothelial dysfunction and hypertension." (PMID 37735515, 2023). "Furthermore, downregulation of Sp1 significantly mitigated the detrimental effects of TGF-β1 on synaptic function, strongly supporting the notion that an increase in Sp1 is essential for the synaptic and cognitive deficits associated with TGF-β1 in AngII-related hypertension." (PMID 40425782, 2025). "Thus, Sp1/Sp3 may be involved in the pathogenesis of hypertension." (PMID 37735515, 2023).
Hypertension (continued). "Meanwhile, in hypertensive rats, GYY4137 treatment attenuates the transcription activities of KLF-5 via S-sulfuration of specificity protein-1 (SP-1) at Cys-664 92, thus stimulating anti-cancer responses." (PMID 33390834, 2021). "The results shows that, via affecting specificity protein 1 (SP1)/AT1R DNA binding, curcumin down-regulated AT1R expression in A10 cells, reduced AT1R-mediated vasoconstriction, and subsequently prevented the development of hypertension in an Ang II-induced hypertensive model." (PMID 27146402, 2016).
ischemia (8 papers, 2013 to 2023). A hypoperfusion of the BLOOD through an organ or tissue caused by a PATHOLOGIC CONSTRICTION or obstruction of its BLOOD VESSELS, or an absence of BLOOD CIRCULATION. "The loss of Sp1/Sp3 delayed the angiogenesis in neonatal retinas, reparative angiogenesis to hindlimb ischemia and skin wound, even the angiogenesis in the subcutaneous tumor." (PMID 37735515, 2023). "Through the activation of the endogenous SP1 gene or the reduction of SP1 degradation, it is possible to promote its role as an antioxidant and attenuate the damage caused by ischemia." (PMID 34970121, 2021). "Our results, for the first time, demonstrate that kidney ischemia-reperfusion injury decreases renal folate transporter expression, in part, mediated via Sp1 transcriptional downregulation and causes a significant reduction of plasma folate levels in a rat model." (PMID 34149715, 2021). "A previous study also noted increased SP1 expression in the cortex after brain I/R damage and in primary neurons post-OGD/R, providing novel insights into the endogenous pathways that prevent ischemia-associated neuronal injury." (PMID 33424542, 2020). "Interestingly, ischemia increases the levels of GLUT-1 in the brain via Sp1, a transcription factor that has specific binding sequences within the GLUT-1 gene as well as within the EGF-R promoter." (PMID 23763269, 2013). "Sp1 has also been shown to regulate SK1 in humans; for instance, Sp1 has been demonstrated to be packaged and transported in exosomes to upregulate SK1 in nearby cells, which protects from ischemia/perfusion injury." (PMID 33171624, 2020). "However, SP1 does not just simply exert a protective effect on neurons and glial cells under ischemia or OGD/R, as there has evidence that it can also exacerbate the damage caused by ischemia." (PMID 34970121, 2021).
ischemic stroke (8 papers, 2017 to 2024). A stroke disorder caused by obstruction of blood flow to the brain, due to thrombotic (local blood clot formation) or embolic (due to a blood clot or other material traveling from another site) event. "In this review, we highlight the roles of SP1 in ischemic stroke and shed light on the underlying mechanism." (PMID 34970121, 2021). "In this review, we have provided clear insight into the role of SP1 in ischemic stroke and further explored the therapeutic strategies associated with SP1 in ischemic stroke." (PMID 34970121, 2021). "Yan Feng and his team indicated that miR-1224 suppresses NK cell function through Sp1 after ischemic stroke, especially in the periphery." (PMID 38835783, 2024). "We further investigated the mechanism of regulating CIRP expression in ischemic neurons and identified sp1 as its transcription factor, which is increased after ischemic stroke and mainly co-localizes with neurons." (PMID 38377019, 2024). "The role of SP1 in ischemic stroke can be divided into two different kinds, protective and damaging." (PMID 34970121, 2021). "In the future, the role of SP1 in ischemic stroke and related treatment needs detailed investigation to amplify its protective role while dampening its damaging effects." (PMID 34970121, 2021). "When the proinflammatory role of SP1 in ischemic stroke is confirmed, various treatments aimed at its reduction can be learned from similar methods used in the cures of other diseases." (PMID 34970121, 2021). "According to the summary about the role of SP1 in the development of ischemic stroke in this review, it is through the upregulation of SP1 level and the reduction of its degradation that the protective function of SP1 takes effect." (PMID 34970121, 2021). "In summary, our study indicated that miR-1224 suppresses NK cell function through Sp1 after ischemic stroke, especially in the periphery." (PMID 34118948, 2021). "Conversely, taking into account its deteriorating effects in ischemic stroke, it is necessary to reduce the SP1 level or disturb and attenuate its downstream results." (PMID 34970121, 2021). "In this review, we present a comprehensive overview on the roles of SP1 as both an antioxidant and anti-apoptotic agent, as well as how it affects the cytosolic ion transporters and promotes inflammation in ischemic stroke events." (PMID 34970121, 2021). "Although many studies and reports on SP1 affecting inflammatory factors in neurodegenerative diseases are currently available, the relationship between SP1 and inflammatory factors in ischemic stroke still needs further investigation." (PMID 34970121, 2021). "SP1 expression has been reported to be upregulated following experimental ischemic stroke and can be regulated by NF-κB; thus, it is possible that upregulation of SP1 contributes to the elevation in sEH expression." (PMID 29178914, 2017). "Quite importantly, SP1 plays an antioxidant role during ischemic stroke." (PMID 34970121, 2021). "Ischemic stroke occurs when local blood flow to the brain is interrupted, followed by the hypoxia in nerve cells, glial cells, and endothelial cells in the ischemic region, where SP1 is upregulated and on the act." (PMID 34970121, 2021). "Further studies on the role of SP1 in ischemic stroke should focus on clarifying the periods and stages when SP1 exerts different effects, the situations where its effects tend to be protective or damaging, and the factors that influence the manifestations of its diverse effects." (PMID 34970121, 2021). "Therefore, the role of Cox-2, which is upregulated by SP1, in the oxidative stress state of neurons and glial cells during the onset of ischemic stroke needs to be further explored." (PMID 34970121, 2021). "Analogous to hemorrhagic stroke, the upregulation of SP1 may enhance the effect of selenium in ischemic stroke." (PMID 34970121, 2021).
ischemic stroke (continued). "We wished to further explore whether miR-1224 suppresses NK cell function through the Sp1 pathway after ischemic stroke." (PMID 34118948, 2021). "We found that miR-1224 may suppress NK cell function through the Sp1 pathway after ischemic stroke." (PMID 34118948, 2021). "From the miRNA–mRNA regulatory network, two target genes (SP1 and AGO1) are speculated to be the primary genes of ischemic stroke." (PMID 32744319, 2020). "Using the miRNA–mRNA interaction pairs, two target genes (specificity protein 1 (SP1) and Argonaute 1 (AGO1)) were speculated to be the primary genes of ischemic stroke." (PMID 32744319, 2020). "Different studies have provided different answers as to whether SP1 plays a positive or a negative role in ischemic stroke." (PMID 34970121, 2021). "In addition, the transcription factor specific protein 1 (SP1), nuclear factor of kappa light polypeptide gene enhancer in B-cells 1 (NF-κB1) and signal transducer and activator of transcription 3 (STAT3) may be key transcription factors in the treatment of ischemic stroke with kaempferol." (PMID 36293548, 2022).
myocardial ischemia (8 papers, 2016 to 2024). A disorder of cardiac function caused by insufficient blood flow to the muscle tissue of the heart. "Previously, luteolin pretreatment has been proven to enhance SERCA2a expression by up-regulation of the Sp1 transcription factor to reduce myocardial ischemia/reperfusion injury." (PMID 38419895, 2024). "The expression of SERCA2a after myocardial ischemia/reperfusion (I/R) injury was significantly reduced when transfected with SP1 knockdown adenovirus, suggesting that SP1 can promote SERCA2a expression at the transcriptional level." (PMID 38033852, 2023). "For example, studies in a model of murine myocardial ischemia/reperfusion show a time-dependent induction of cardiac CD39 mRNA under the control of SP1." (PMID 37325567, 2023). "In conclusion, during myocardial ischemia/reperfusion, Sp1 appeared to downregulate the expression of SERCA2a." (PMID 32958799, 2020). "Our experimental results indicated that during myocardial ischemia/reperfusion injury, luteolin pretreatment upregulated the expression levels of SERCA2a and Sp1." (PMID 32958799, 2020). "Luteolin pretreatment was shown to improve SERCA2a expression via the upregulation of Sp1 to attenuate myocardial ischemia/reperfusion injury." (PMID 32958799, 2020). "A mechanism for SP1-regulated induction of cardiac CD39 has been reported in tissue protection during myocardial ischemia." (PMID 26998750, 2016). "Thus, the results implicate that, at the transcriptional level, Lut pretreatment was shown to improve SERCA2a expression via the upregulation of Sp1 to attenuate myocardial ischemia/reperfusion injury." (PMID 32958799, 2020).
osteoarthritis (8 papers, 2014 to 2024). A noninflammatory degenerative joint disease occurring chiefly in older persons, characterized by degeneration of the articular cartilage, hypertrophy of bone at the margins and changes in the synovial membrane. "Functional analysis revealed that the s allele of the Sp1 polymorphism, linked to osteoarthritis and osteoporosis, is associated with enhanced DNA-protein binding, increased transcription, and higher production of collagen type Iα1 mRNA and protein." (PMID 38392197, 2024). "Downregulation of lncRNA NKILA enhanced apoptosis and reduced proliferation of chondrocytes by targeting miR-145, SP1 and NF-κB in osteoarthritis." (PMID 37779916, 2023). "The LINC00511/miR-150-5p/SP1 feedback loop in osteoarthritis (OA) was proven to master the extracellular matrix synthesis of chondrocyte." (PMID 35356768, 2022). "For example, considering the regulation between OP miRNAs and their targets BMP2 and SP1 in the ‘Osteoarthritis Pathway” and “TGF-beta signaling pathway,” BMP2 are functional in osteoblast differentiation." (PMID 32194637, 2020).
rhabdomyosarcoma (8 papers, 2015 to 2025). A rare aggressive malignant mesenchymal neoplasm arising from skeletal muscle. "In alveolar rhabdomyosarcoma (ARMS), the orphan nuclear receptor 4A1 (NR4A1) is responsible for G9a overexpression by complexing with the Sp1 transcription factor (Sp1) and occupying the -511 GC-rich region of the G9a promoter." (PMID 35740522, 2022). "In RD and Rh30 rhabdomyosarcoma (RMS) cells, Methyl 2-trifluoromethyl-3,11-dioxo-18β-olean-1,12-dien-3-oate (CF3DODA-Me)can downregulate the expression of SP1 by inducing ROS." (PMID 34744749, 2021). "Studies on normal cell transformation into cancer cell lines show that this transformation process is accompanied by increased levels of Sp1 in most cell models, and in the transformation of muscle cells into rhabdomyosarcoma, both Sp1 and Sp3, but not Sp4, are increased." (PMID 36982239, 2023). "Rhabdomyosarcomas (RMS) express high levels of Sp1 compared to non-transformed muscle tissue and RMS cell lines express high levels of Sp1, Sp3 and Sp4." (PMID 36982239, 2023). "Inhibition of SP family (SP1, SP3 and SP4) could suppress rhabdomyosarcoma cell and tumor growth via non-steroidal anti-inflammatory drug (NSAID) tolfenamic acid (TA)." (PMID 35847857, 2022).
autoimmune disease (7 papers, 2013 to 2025). A disorder resulting from loss of function or tissue destruction of an organ or multiple organs, arising from humoral or cellular immune responses of the individual to their own tissue constituents. "The identified targets TGFBR1 and IGF1R have been shown to be downregulated in blood cells of patients with autoimmune disease and a loss of SP1 and knockdown of GNAI1 have been described to impair hematopoiesis and immune cell migration capability, respectively." (PMID 31569706, 2019). "This retrospective study evaluated the clinical relevance of the three novel autoantibodies, anti-SP1, anti-CA6, and anti-PSP, in patients with clinically significant aqueous-deficient dry eye who were suspected of having an underlying autoimmune disease, particularly SS." (PMID 30766890, 2019). "In addition, Sp1 is capable of interacting with NF-κB to play a critical role in autoimmune disease and cancer." (PMID 23301086, 2013).
chronic myeloid leukemia (7 papers, 2015 to 2025). "In some chronic myeloid leukemia (CML) cell lines, Ras upregulates p21 expression, and activation of the p21 promoter by Ras was dependent on Sp1/3 binding sites." (PMID 26499944, 2016). "Doxorubicin treatment up-regulates Sp1 protein and mRNA levels in the human breast adenocarcinoma MCF-7 and chronic myeloid leukemic cell line K562 cells, respectively." (PMID 26271039, 2015).
endothelial dysfunction (7 papers, 2015 to 2025). In vascular diseases, endothelial dysfunction is a systemic pathological state of the endothelium (the inner lining of blood vessels) and can be broadly defined as an imbalance between vasodilating and vasoconstricting substances produced by (or acting on) the endothelium. "Studies have shown that endothelial cell-specific SP1/SP3 deficiency leads to endothelial dysfunction, primarily by regulating the expression of AMPKa." (PMID 39062521, 2024). "SP1 is implicated in the regulation of apoptosis, cell hypertrophy, inflammation, oxidative stress, lipid metabolism, plaque stabilization, endothelial dysfunction, fibrosis, calcification, and other pathological processes." (PMID 39062521, 2024). "To further explore the molecular mechanism by which Sp1 and Sp3 regulate endothelial function, we used Ang II, implicated in the pathogenesis of endothelial dysfunction, as a representative stimulus." (PMID 37735515, 2023). "Furthermore, H2S can upregulate VEGFR-2 via the S-sulfhydration of Sp1, promoting the proliferation and migration of VECs, and thereby ameliorating endothelial dysfunction induced by CBS deficiency." (PMID 39252788, 2024). "In summary, the mechanism by which the eNOS/NO system ameliorates endothelial dysfunction involves the phosphorylation of Sp1." (PMID 39252788, 2024). "Emerging data indicate the pivotal involvement of SP1 in key processes during atherosclerosis (AS) progression, such as inflammation, lipid metabolism, plaque stability, endothelial dysfunction, and fibrosis." (PMID 39062521, 2024). "SP1 regulates processes like inflammation, lipid metabolism, plaque stability, endothelial dysfunction, and fibrosis, thereby delaying the progression of cardiac remodeling." (PMID 39062521, 2024). "Sp1 phosphorylation plays a crucial role in mitigating atherosclerotic plaque formation, contributing plaque stability, maintaining cholesterol homeostasis (Thr453/739), and regulating to endothelial dysfunction." (PMID 39252788, 2024). "The activity of the antioxidant N-acetyl-L-cysteine (NAC) decreased the protein levels of Sp1 and Sp3 induced by Ang II, which suggests that Ang II aggravated endothelial dysfunction by promoting reactive oxygen species (ROS) and reducing Sp1 and Sp3 expression." (PMID 37735515, 2023). "Taken together, these data indicate that Sp1 and Sp3 deletion abolished the captopril-induced alleviation of endothelial dysfunction and the anti-apoptotic effects of captopril in endothelial cells; Sp1 and Sp3 have an indispensable role in the success of captopril treatment in the endothelium." (PMID 37735515, 2023). "Moreover, induced by SP1, miR-320a downregulated SRF, a key endothelial cell regulator essential for VGEF induced cell signalling and angiogenesis, and contributed to endothelial dysfunction." (PMID 25728840, 2015).